VEGFB (vascular endothelial growth factor B)
Description:
Growth factor for endothelial cells. VEGF-B167 binds heparin and neuropilin-1 whereas the binding to neuropilin-1 of VEGF-B186 is regulated by proteolysis.
Synonyms: VRF; VEGFL
Tractability: Antibody: its Gene Ontology location is reachable by antibodies, with high confidence; UniProt places it where antibodies can reach, with medium confidence; UniProt predicts a signal peptide or a membrane-spanning region. Other modalities: a drug acting on it is in phase 2 or 3 trials.
Target class: Secreted protein
Safety:
Unwanted effects reported when the protein is acted on. In parentheses: how it was acted on, where the effect was seen, and who reports it.
dermatologic toxicity (source: ClinPGx)
Gene: Protein-coding gene on chromosome 11 (64,234,521 to 64,239,264, forward strand). Ensembl gene ENSG00000173511.
Subcellular location: Secreted
Pathways (Reactome):
Signal Transduction: VEGF binds to VEGFR leading to receptor dimerization; VEGF ligand-receptor interactions
Hemostasis: Platelet degranulation
Gene Ontology:
Molecular function: protein binding; chemoattractant activity; growth factor activity; vascular endothelial growth factor receptor binding; receptor ligand activity
Biological process: vascular endothelial growth factor signaling pathway; induction of positive chemotaxis; positive regulation of mast cell chemotaxis; response to hypoxia; sprouting angiogenesis; vascular endothelial growth factor receptor signaling pathway; positive chemotaxis; positive regulation of cell population proliferation
Cellular component: growth factor complex; extracellular region; platelet alpha granule lumen; membrane
Genetic constraint (gnomAD): Loss-of-function variants: 24 observed, 21.8 expected, observed/expected ratio (o/e) 1.1, 90% interval 0.8 to 1.55. The synonymous counts are far from expectation, so gnomAD's model fits this gene poorly and the ratio says little. Missense variants: 327 observed, 270.7 expected, observed/expected ratio (o/e) 1.21, 90% interval 1.1 to 1.32. Synonymous variants: 141 observed, 110.46 expected, observed/expected ratio (o/e) 1.28, 90% interval 1.11 to 1.47.
Homologues: Orthologues: chimpanzee VEGFB (100% identical), macaque VEGFB (98% identical), pig VEGFB (94% identical), guinea pig VEGFB (89% identical), rat Vegfb (76% identical), dog VEGFB (64% identical), mouse Vegfb (62% identical), zebrafish vegfba (26% identical), zebrafish vegfbb (15% identical). Paralogues in human: VEGFA (28% identical), PGF (22% identical), VEGFD (18% identical), VEGFC (17% identical).
Diseases named in the same sentence as VEGFB in open-access papers:
VEGFB is named in the same sentence as 193 diseases in open-access papers, as found by Europe PMC text mining. Sharing a sentence is not in itself a finding about the gene and the disease. The quoted sentences say what the papers report.
diabetes (23 papers, 2012 to 2026). "In conclusion, we suggest that using VEGFB as a cardio protective therapy in diabetes is an intriguing concept and should be explored." (PMID 29732375, 2018). "Although the role of VEGFB in angiogenesis and cell death is an emerging topic, its connection to diabetes is in its infancy." (PMID 29732375, 2018). "It should also be noted that one third of patients with diabetes show signs of diabetic retinopathy and higher levels of VEGFB have been reported in the vitreous of patients with diabetic ocular disease." (PMID 29732375, 2018). "In addition to cardiomyopathy, diabetic retinopathy is also a major consequence of diabetes and human retinal endothelial cells cultured in high glucose displayed decreased VEGFB gene expression." (PMID 29732375, 2018). "Although vascular endothelial growth factor b (VEGFb) might have an impact on the development of obesity, diabetes and related disorders, the possible relationship between VEGFb serum levels and the incidence of these metabolic complications in humans is still unknown." (PMID 35987953, 2022). "In particular, vascular endothelial growth factor B (VEGF-B) has been described in cardiovascular disease, diabetes, and cancer; however, its function in ophthalmology remains poorly understood, as it is the most controversial molecule of the VEGF family." (PMID 29099033, 2017). "Our results also demonstrated that DNA methylation of VEGFB was lower in diabetes and its cardiovascular diseases groups than that in the normal group." (PMID 36875456, 2023). "VEGFA was not affected by diabetes, whereas VEGFB was significantly downregulated (p < 0.001 vs the control group)." (PMID 31001672, 2019). "Diabetes induced an increase in immunoreactive ANGPT2 (p < 0.05) but did not alter ANGPT1, VEGFA, VEGFB, IGFBP2 or SEMA6A." (PMID 31001672, 2019).
myocardial infarction (17 papers, 2014 to 2025). Gross necrosis of the myocardium, as a result of interruption of the blood supply to the area, as in coronary thrombosis. "The expression of VEGFB in mice myocardial models with myocardial infarction or heart failure induced by aortic coarctation was both significantly downregulated." (PMID 38775031, 2024). "In another human study, patients that had suffered an acute myocardial infarction (AMI) displayed increased plasma VEGFB compared to healthy volunteers." (PMID 29732375, 2018).
cardiac hypertrophy (16 papers, 2014 to 2025). "Preclinical studies have shown the therapeutic potential of VEGF-B (vascular endothelial growth factor B) in revascularization of the ischemic myocardium, but the associated cardiac hypertrophy and adverse side effects remain a concern." (PMID 38655691, 2024). "The observation that AAV9-Vegfb treatment had a mild mitotic effect on cardiac endothelial cells suggests that VEGFB induces endothelial proliferation and thereby protects from cardiac hypertrophy related capillary density decline." (PMID 40116846, 2025). "Cardiac single-nucleus RNA sequencing of the hearts and in vitro analysis of the cardiomyocytes indicated up-regulation of the STAT3 signal transduction pathway as a potential contributor of VEGFB-induced cardiac hypertrophy." (PMID 40116846, 2025). "Molecular markers such as vascular endothelial growth factor B, growth/differentiation factor 15, and glycoprotein 130 also play crucial roles in myocardial hypertrophy development." (PMID 38994368, 2024). "Vascular endothelial growth factor-B (VEGF-B) promotes coronary arteriogenesis, physiological cardiac hypertrophy, and ischemia resistance." (PMID 34386529, 2021). "Such non-cell-autonomous mechanism was also triggered by overexpression of the related transcription enhancer factor-1 RTEF1 in endothelial cells, which induced cardiac hypertrophy in response to aortic constriction through an increase of VEGFB protein level." (PMID 29396779, 2018). "The two main candidate genes in Collas are associated with heart performance, one by increasing its vascularisation (VEGFB) and the other by regulating cardiac hypertrophy (ELDT1)." (PMID 24686296, 2014). "Vascular endothelial growth factor-B (VEGF-B) regulates the proliferation, sprouting, and migration of ECs and can potentially induce coronary vessel growth and cardiac hypertrophy." (PMID 38987722, 2024). "In genome-wide scans of extended haplotype homozygosity Collas showed the strongest signal around VEGFB, which plays an essential role in the ischemic heart, and ELTD1, another gene crucial for heart development and prevention of cardiac hypertrophy." (PMID 24686296, 2014). "Vascular endothelial growth factor-B (VEGF-B), one of the five known members of VEGF that regulate endothelial function, has been demonstrated to show potent in promoting coronary arteriogenesis and physiological cardiac hypertrophy." (PMID 35282350, 2022). "In addition, molecular biomarkers including vascular endothelial growth factor B, NAD‐dependent deacetylase sirtuin‐3, growth/differentiation factor 15 and glycoprotein 130, also play important roles in the development of myocardial hypertrophy." (PMID 30648807, 2019). "Although studies of Lauriol and colleagues did not reveal enhanced expression of VEGFB mRNA level, they did not exclude a possible implication of SHP2 in NSML cardiac hypertrophy that employs this RTEF1-VEGF signaling mechanism." (PMID 29396779, 2018).
Obesity (14 papers, 2017 to 2024). Accumulation of substantial excess body fat. "Sedentary individuals have lower VEGFB production and are likely to deposit diet fats in ectopic fat depots and develop obesity." (PMID 35987953, 2022). "Vascular endothelial growth factor B (VEGFB) was regarded to improve lipid metabolism and reduce obesity-related hyperlipidemia." (PMID 35907871, 2022). "Studies have confirmed that VEGFB can inhibit HFD-induced weight gain to reduce obesity and ameliorate insulin resistance." (PMID 35907871, 2022). "VEGFB may play a role in diet induced obesity and free fatty acid uptake by the endothelial cells in skeletal muscle, but this remains controversial." (PMID 31877123, 2019). "This indicates that the SBC, VEGFB, likely plays a significant role in the observed effect of serum TGs on NAFLD that is induced by obesity-related adipose dysfunction." (PMID 37224770, 2023). "Some studies have reported increased circulating and adipose tissue VEGFb levels in individuals with obesity compared to lean subjects, but the results have not been reproduced by other authors." (PMID 35987953, 2022).
ovarian carcinoma (13 papers, 2003 to 2025). A malignant neoplasm originating from the surface ovarian epithelium. "We tested the potential prognostic role of miR-484 and of its target VEGFB, previously associated with higher platinum sensitivity in high grade ovarian cancer." (PMID 34680301, 2021). "hsa-miR-484, which was upregulated in R2 vs. HC, is associated with chemoresistance in ovarian cancer due to enhanced angiogenesis, resulting from modulation of the tumor vasculature, through regulation of VEGFB and VEGFR2 pathways." (PMID 28970833, 2017). "Decreased VEGFB expression is associated with improved survival and may be an indicator of response to anti-angiogenic therapies in ovarian cancer patients." (PMID 26083629, 2015). "The results showed that high expression of VEGFB was positively correlated with survival probabilities in specific tumors, such as pancreatic ductal adenocarcinoma, ovarian cancer, sarcoma, esophageal squamous cell carcinoma, and others." (PMID 39145452, 2024). "More intriguing are the results showing no inverse correlation between VEGFB and miR-484 expression in the analyzed samples based on the knowledge that VEGFB is a bona fide miR-484 target in ovarian cancer cells." (PMID 34680301, 2021). "Using in vivo mouse studies with miR-484 stably transduced ovarian cancer cell lines, more chemosensitive tumors resulted due to regulation of VEGFB and VEGFR2 by miR-484." (PMID 24641801, 2014). "It was deduced that the expression of VEGFB in ovarian cancer, colorectal cancer, renal cancer and prostate cancer was significantly upregulated, so it may play a role in the initial stage of tumorigenesis." (PMID 38775031, 2024). "Finally, based on our previous results showing that miR-484 targets VEGFB in ovarian cancer cells, we closer examined their behavior in the studied population." (PMID 34680301, 2021). "MicroRNA-484 directly targets VEGFB and VEGFR2, thereby defining chemoresistance in ovarian cancer through modulation of tumor vasculature." (PMID 24865854, 2014). "Similarly, treatment with fucoidan repressed the mRNA expression of angiogenesis related genes including VEGFA, VEGFB, VEGFC, VEGFD, FLT-1, FLT-4, and KDR in the ovarian cancer cells." (PMID 31936539, 2020). "In addition, the expression of VEGFB decreased in fucosterol-treated ovarian cancer cells compared to non-treated cells." (PMID 32429354, 2020).
heart failure (12 papers, 2014 to 2025). Inability of the heart to pump blood at an adequate rate to meet tissue metabolic requirements. "Association between the VEGFB SNPs and heart failure seems probable due to VEGFB’s role in cardioprotection." (PMID 39684876, 2024). "Conversely, multiple models of heart failure, including diabetic cardiomyopathy, have indicated a significant drop in VEGFB." (PMID 29732375, 2018). "Overall, VEGFB appears to be important for tissue protection, whether this occurs in the context of heart failure or neuronal degeneration." (PMID 39684876, 2024). "Vascular endothelial growth factor B (VEGFB) may be one growth factor that plays an important role in protecting against heart failure." (PMID 29732375, 2018). "Although VEGFB’s potential therapeutic role in heart failure remains promising, current evidence is limited to preclinical investigations, and further research is needed to fully understand its mechanisms of action, such that VEGFB-mediated targeted interventions can be developed." (PMID 41148858, 2025). "In addition, through its actions promoting cell survival, VEGFB could limit cardiac cell death and help delay heart failure." (PMID 29732375, 2018). "However, within the AMI group, those patients that were on the lower scale of the plasma VEGFB spectrum prior to discharge, exhibited increased left ventricular remodeling six months post MI, a marker for potential left ventricular dysfunction and heart failure." (PMID 29732375, 2018).
Insulin resistance (12 papers, 2012 to 2025). Increased resistance towards insulin, that is, diminished effectiveness of insulin in reducing blood glucose levels. "This study investigated the involvement of VEGFB in lipid metabolism and insulin resistance via the AMPK signaling pathway in NAFLD." (PMID 35907871, 2022). "Despite targeting VEGFB as a novel treatment for insulin resistance and type 2 diabetes, our results showed that the knockdown of VEGFB did not affect the glucose tolerance and insulin tolerance." (PMID 35886871, 2022). "VEGFB can participate in lipid metabolism and insulin resistance of NAFLD through the AMPK signaling pathway." (PMID 35907871, 2022). "Our study showed that in NAFLD mice with VEGFB knockout, blood glucose level increased markedly, glucose tolerance was impaired, insulin resistance was distinct, and insulin sensitivity descended." (PMID 35907871, 2022). "Our study showed that VEGFB regulates the abnormal lipid metabolism and insulin resistance of NAFLD through AMPK signaling pathway." (PMID 35907871, 2022). "In conclusion, our study proved that VEGFB can participate in lipid metabolism and insulin resistance of NAFLD via the AMPK signaling pathway." (PMID 35907871, 2022). "Vascular endothelial growth factor B (VEGF-B) is a critical metabolic regulator in insulin resistance, and lipid distribution." (PMID 33408593, 2020). "Additionally, vascular endothelial growth factor B (VEGFB) has been shown to improve insulin resistance and lipid metabolism by modulating the PI3K/AKT pathway." (PMID 41262444, 2025). "Our study found that VEGFB knockout could accelerate the development of insulin resistance." (PMID 35907871, 2022). "After the systemic VEGFB knockout mice were fed with high fat, the body fat, serum lipoprotein, NAFLD score, and insulin resistance were increased." (PMID 35907871, 2022).
pancreatic cancer (12 papers, 2010 to 2024). "Metformin and resveratrol synergistically block pancreatic cancer cell proliferation in vitro and in vivo by inhibiting vascular endothelial growth factor B (VEGF-B) signaling pathway." (PMID 30147674, 2018). "A recent study showed that in pancreatic cancer cells, metformin potentiates the anti-tumor activity of resveratrol by inhibiting vascular endothelial growth factor b (VEGF-B) signaling pathway." (PMID 27902459, 2017). "By down-regulating vascular endothelial growth factor b signaling pathway, metformin enhances anti-tumor effects of resveratrol on pancreatic cancers." (PMID 28903435, 2017). "NGF beta, VEGFB, and IGF-II are growth factors related to pancreatic cancer progression." (PMID 37903909, 2024). "Driver genes have been identified as the building blocks in pancreatic cancer, and emerging data suggested that driver gene K-Ras involved in the process of splicing control, such as mucin 6 (MUC6), hepatocyte growth factor (HGF), VEGFR-2, and VEGFB." (PMID 31552163, 2019). "VEGFB has been found to be able to promote migration and invasion, but not proliferation or survival in pancreatic cancer cells." (PMID 24926961, 2014).
ischemia (11 papers, 2011 to 2025). A hypoperfusion of the BLOOD through an organ or tissue caused by a PATHOLOGIC CONSTRICTION or obstruction of its BLOOD VESSELS, or an absence of BLOOD CIRCULATION. "This corresponds well to the increased activity of the prosurvival VEGFB in the area of the ischemia and the more proangiogenic VEGFA on the contralateral side." (PMID 21912702, 2011). "Previous studies have demonstrated that VEGFB plays a pivotal role in cardiovascular health, particularly in modulating mitochondrial function and cellular survival under stress conditions such as ischemia." (PMID 41148858, 2025). "In brief, VEGFB reduced hypoxia-induced cell death of mouse cortical neurons in culture and mice lacking VEGFB were more susceptible to ischemia-induced brain damage." (PMID 40050849, 2025). "In the experimental model of myocardial ischemia, linalool inhibited the inflammatory response, prevented oxidative stress, and increased the level of vascular endothelial growth factor B, thereby providing protection against ischemia-induced cell death and apoptosis." (PMID 32670059, 2020). "In summary, our data indicate that VEGFB and VEGFA and their receptors are up-regulated by candesartan in the brain after ischemia and the changes are seen differentially in both hemispheres." (PMID 21912702, 2011).
Parkinson disease (11 papers, 2009 to 2025). A progressive degenerative disorder of the central nervous system characterized by loss of dopamine producing neurons in the substantia nigra and the presence of Lewy bodies in the substantia nigra and locus coeruleus. "Administration of VEGFB was also neuroprotective in cultures of dopaminergic neurons from Parkinson’s disease (PD) rat models, as well as in in vivo PD rat models." (PMID 40050849, 2025). "For the first time, we provide evidence that VEGFB expression in inhibitory neurons may relate to a protective effect against AD neuropathology as has been hypothesized previously and observed in models of Parkinson's disease." (PMID 39641382, 2025).
type 2 diabetes (11 papers, 2018 to 2026). "Inhibition of vascular endothelial growth factor B (VEGFB) has been shown to counter these factors associated with abnormal cardiac metabolism by inducing metabolic flexibility and preventing cardiac lipid accumulation in Type 2 diabetes." (PMID 41788807, 2026). "As cardiomyopathy is also a feature of Type 2 diabetes, the role of VEGFB in progression of heart dysfunction in animal models of T2D is also of interest and should be examined." (PMID 29732375, 2018). "Moreover, inhibition of VEGFB expression could prevent the progression of type 2 diabetes and restore insulin sensitivity in mice fed a high-fat diet." (PMID 36875456, 2023).